APOB (apolipoprotein B)
Diseases named in the same sentence as APOB in open-access papers (continued):
Sharing a sentence is not in itself a finding about the gene and the disease.
coronary artery disease (continued). "Compared with the unlikely FH patients with ACS, the FH patients had higher levels of TC, LDL-c, apoB, Lp(a), non-HDL-c, TC/HDL-c and apoB/apoA1 ratio, more severe coronary artery diseases and greater prevalence of left main and triple or multiple vessel lesions." (PMID 38443803, 2024). "In the present study, along with elevated LDL-cholesterol, several blood lipid profiles, including non-HDL-c, apoB, Lp(a), TC/HDL-c and apoB/apoA1 ratio, were significantly increased and were associated with the severity of coronary artery disease in FH patients." (PMID 38443803, 2024). "The overall certainty of the evidence was high for LDL cholesterol, total cholesterol, non-HDL cholesterol, triglycerides, apolipoprotein B and body weight and moderate for HDL cholesterol, systolic blood pressure, diastolic blood pressure, CRP and estimated 10-year coronary heart disease risk." (PMID 31540227, 2019). "However, most recently a larger study including 748 cases and 1723 controls showed that IgG and IgM autoantibodies to MDA-LDL and apoB immune complexes were not independent predictors of coronary artery disease." (PMID 25768285, 2015). "The last serum lipid marker evaluated in this analysis, LDL, is another key biomarker for hyperlipidemia and coronary heart disease (CHD), alongside other factors such as small dense LDL (sd-LDL), non-high-density lipoprotein cholesterol (non-HDL-c), and Apolipoprotein B (ApoB)." (PMID 39839806, 2024). "Compared with the unlikely FH patients, FH patients with ACS had higher levels of TC, LDL-c, apoB, Lp(a), non-HDL-c, TC/HDL-c and apoB/apoA1 ratio and had more serious coronary diseases and greater prevalence of left main, triple-, or multiple-vessel lesions at the time of discharge." (PMID 38443803, 2024). "ApoB-depleted plasma was used to assess the cholesterol efflux capacity of HDL, an anti-atherogenic property of HDL, which has been shown to be inversely correlated with coronary artery disease, independent of HDL-cholesterol concentrations." (PMID 37107170, 2023).
Hypertension (270 papers, 2006 to 2026). The presence of chronic increased pressure in the systemic arterial system. "Advanced age, increased BMI, hypertension, raised TG,and high ApoB were associated with an increased risk of T2DM in adult SMDpatients." (PMID 41209502, 2025). "Hypertension (OR = 3.53, P < 0.01) and HbA1c (OR = 1.37, P = 0.048) persisted as significant risk factors, whereas ApoB (OR = 0.66, P < 0.01) demonstrated a protective association." (PMID 41299285, 2025). "In this patient cohort, our study found that age, body mass index (BMI), hypertension, triglyceride levels and apolipoprotein B levels were important risk factors for T2DM." (PMID 41209502, 2025). "Thisinvestigation found advanced age, increased BMI, hypertension, raised TG, andhigh ApoB to be risk factors for comorbid T2DM in individuals with SMD." (PMID 41209502, 2025). "They found that hCRP correlated with disease severity (PASI score) and the ApoB/ApoA1 ratio, while metabolic parameters were linked to blood pressure, hypertension, weight, and BMI." (PMID 40137160, 2025). "Patients with SSNHL had a higher risk of concomitant hypertension and elevated atherosclerogenic lipid levels, with apolipoprotein B and apolipoprotein E identified as independent risk factors for the onset of SSNHL." (PMID 38714080, 2024). "Both in pre-symptomatic individuals and controls, current smoking, hypertension, and an elevated ApoB:ApoA1 ratio were significantly associated with a future CVE, whereas an elevated BMI was significant only in the controls." (PMID 36362763, 2022). "The baseline apoB level was positively associated with the odds of incident hypertension over 10 years." (PMID 36551995, 2022). "The association between apoB with the risk of hypertension was analyzed in middle-aged and older women." (PMID 36551995, 2022). "Of all characteristics, significant association was only noted for hypertension and omnibus haplotypes in ApoB gene (Simulated P = 0.001)." (PMID 33889589, 2021). "As expected, we have observed a significant association between omnibus haplotypes in ApoB gene and hypertension." (PMID 33889589, 2021). "Associations between apoB and self-reported outcomes in first-degree relatives were characterised for 12 diseases (including heart disease, stroke, and hypertension) and parental vital status together with age at death." (PMID 34729547, 2021). "In our study, mRSS was univariably associated with age, hypertension, apolipoprotein B serum levels, and CEC." (PMID 33622410, 2021). "In further haplotype-phenotype analysis, significant association was only noted for hypertension and omnibus haplotypes in ApoB gene (PSimulated = 0.001)." (PMID 33889589, 2021). "Further, logistic regression analysis revealed that high LDL-C, high ApoB, smoking, hypertension and the ε4 allele were risks for the presence of CI." (PMID 32891149, 2020). "In the subgroup analysis, no clear differences were found in associations between numbers of vascular lesions and the ApoB/A1 ratio according to strata of age, smoking, drinking, and hypertension." (PMID 31744496, 2019). "In the meanwhile, foods high in fat and salt can cause hypertension, higher levels of serum TG as well as ApoB in the Maonan compared to the Han." (PMID 31862910, 2019). "(i) The APOB p.E4181K polymorphism (under the dominant model) is associated with an increased risk for hypertension." (PMID 25587205, 2014). "The first was observed for APOB p.E4181K, which increased the risk of developing essential hypertension under the dominant model (EK+KK v." (PMID 25587205, 2014). "Notable suggestive loci observed for apoB have been previously associated with adiposity and hypertension." (PMID 24386469, 2013). "In the present investigation, we report a genetic association study on obese and hypertension using three candidate loci (ApoB, LPL and Leptin)." (PMID 19772655, 2009).
Hypertension (continued). "Multivariate logistic regression identified the rs2000813CT genotype, hypertension, ages ≥60 years, body mass index (BMI) values ≥28 kg/m2, total cholesterol (TC) ≥6.2 mmol/L, and apolipoprotein B (ApoB) ≥1.1 g/L as potential risk factors for CHD in women (p < 0.05)." (PMID 40776945, 2025). "However, in subgroups with hypertension, hyperuricemia and hypohemia, the associations between ApoB and CKD disappeared." (PMID 37124758, 2023). "Our study raises some important questions: For instance, it is intriguing to ask whether hypertension remains independently associated with ApoB IgG levels and how arterial hypertension may drive IgG generation." (PMID 35479271, 2022). "In a recent cohort, normotensive Japanese–American men and women (n = 233) aged 46.4 ± 11.0 years were recruited to investigate whether plasma apoB concentration predicted the risk of hypertension over a 10-year study period." (PMID 36551995, 2022). "But only ApoB/ApoA1 was positively correlated with inflammatory marker hCRP and the concomitant of arthritis, and they were all associated with diastolic blood pressure or the concomitant of hypertension, weight, or BMI in a stepwise regression analysis." (PMID 34996506, 2022). "In view of our haplotype-disease and haplotype-phenotype analyses, it is reasonable to speculate that the association of ApoB gene with DKD may be mediated by its association with hypertension, which further precipitates the development of DKD." (PMID 33889589, 2021). "We agree that further studies exploring the concurrent association of ApoB genetic defects with hypertension and DKD are needed to confirm or refute this speculation." (PMID 33889589, 2021). "Dozens of studies have evaluated the genetic susceptibility of ApoB gene to hypertension." (PMID 33889589, 2021). "ApoA1/ApoB was associated with renal function decline and hypertension (P<0.05 for all)." (PMID 33112407, 2020). "High ApoB was also found to be associated with longer duration of hypertension." (PMID 28376848, 2017). "Furthermore, univariate analysis showed that age (p = 0.001), age at disease onset (p = 0.003), arthritis (p = 0.014), weight (p = 0.000), BMI (p = 0.000), hypertension (p = 0.002), and the rs11960458 SNP in AnxA6 (p = 0.014) were significantly associated with ApoB levels." (PMID 36498634, 2022). "These 9 selected predictors included: age, total cholesterol (TC), total protein (TP), white blood cell count (WBC), high-density lipoprotein cholesterol (HDL_C), Apo lipoprotein B (ApoB), triglycerides (TG), hypertension, and body mass index (BMI)." (PMID 40140819, 2025). "Compared with control patients, the level of blood creatinine was increased significantly in hypertension group, but the value of uric acid, urea nitrogen/creatinine, serum potassium, and apolipoprotein B were unchanged in hypertension group." (PMID 40303609, 2025). "Individuals with SMD demonstrate a significant prevalence of comorbid T2DM,especially in older adults with elevated BMI, hypertension, increased TG, andhigh ApoB levels." (PMID 41209502, 2025). "The SMI group had higher levels of male patients, hypertension history,smoking history, BMI, TG, ApoB/A1, UA, LVEDD, Gensini score, FPG and TyG-BMI whencompared to the CCMI group." (PMID 40776971, 2025). "After adjusting for hypertension, HbA1c, ApoB, and BNP (primary model), both muscle volume (OR per 1 SD = 0.60, P < 0.01) and muscle density (OR per 1 SD = 0.65, P = 0.016) remained independently associated with lower odds of CVEs." (PMID 41299285, 2025). "The development of efficacious prevention strategies targeting cardiovascular risk factors such as hypertension, LDL cholesterol, and other ApoB (apolipoprotein-B) containing lipoproteins has revolutionized the care of these conditions." (PMID 41190437, 2025).
Hypertension (continued). "The principal findings of the univariate logistic regression analysis indicatethat age, non-marital status, educational attainment, BMI, type of SMD,hypertension, fatty liver, TG, HDL-C, ApoB, and TC are associated with theoccurrence of T2DM." (PMID 41209502, 2025). "In the biomarker-disease co-expression network, APOB was associated with the highest number of diseases significantly linked to OSCC, while GLP1R predicted only two diseases, including hypertensive disease, which was co-predicted by both APOB and GLP1R." (PMID 40696350, 2025). "In a Chinese cohort of 1,228 participants with type 2 diabetes mellitus, polymorphisms in ApoB and PCSK9 were associated with hypertension and diabetic kidney disease (DKD)." (PMID 41573461, 2025). "This is the first study to explore the relationship between serum ApoB levels and the risk of ACM and CVM in individuals with hypertension." (PMID 38789961, 2024). "After adjustments for pre-pregnancy BMI, age at delivery, hypertensive disorders, gestational diabetes and conception method, our study discerned ApoA, ApoB, CHOL and TG lipid profiles in early pregnancy as independent risk factors for the development of PTB." (PMID 38734779, 2024). "When tested as a linear variable, the ApoB/ApoA-I ratio was higher in younger patients, current or former smokers, and those with a history of hypertension, high levels of LDL-C and TG, low levels of HDL-C, and large-artery atherosclerosis (LAA) strokes." (PMID 38274879, 2023). "Some baseline characteristics were similar across all MHR tertiles, including age, hypertension, systolic and diastolic blood pressure, ApoB, and LDL-C." (PMID 37553680, 2023). "Elevated ApoB:ApoA1 ratio in combination with hypertension yielded a higher OR compared with the combination of hypertension with current smoking in the cases, while in controls these risk factor combinations acted to the opposite effect." (PMID 36362763, 2022). "After further adjustment for education level, BMI, hypertension, FBG, and CRP, as well as the use of clozapine, olanzapine, risperidone and quetiapine, higher levels of NHDL-C, and ApoB were still associated with lower odds of cognitive impairment." (PMID 36506447, 2022). "Association of APOB, APOE, and MTHFR polymorphisms with higher lipid levels and the risk of developing hypertension and cardiovascular diseases have been described." (PMID 34616421, 2021). "None of the associations were changed when the main model was further adjusted for the potential mediators ApoB/ApoA-1 ratio, hypertension, and the use of lipid-lowering medications." (PMID 33425973, 2020). "The lowest quartile of ApoB/ApoA1 was predominant for patients with first degree of hypertension (p < 0.05)." (PMID 32717783, 2020). "Only age, ApoB, HDL cholesterol, smoking, and hypertension were associated with SA; being a survivor of GCT and exposure to chemotherapy or radiotherapy were not." (PMID 32244483, 2020). "In this prospective population-based study, high blood pressure, smoking, low apoB,use of oral anticoagulants and living alone were independently associated withincidence of spontaneous ICH." (PMID 33072882, 2020). "Factors independently associated with higher mean low-density lipoprotein cholesterol and apolipoprotein B were female gender, older age, higher education, higher income, obesity, and hypertension." (PMID 31809516, 2019). "In clinics, patients with PDD suffered less hypertension and had lower serum low-density lipoprotein cholesterol and apolipoprotein B levels when compared to the other patients with PD." (PMID 30233306, 2018). "Further, clinical predictors (heart failure, hypertension and heart rate (HR)) and biochemical risk factors (creatinine, BUN, UA, TG, TC, HDL-C, LDL-C, apolipoprotein-A, apolipoprotein-B, and B2M) were involved into multiple logistic regression model." (PMID 28249620, 2017).
Hypertension (continued). "In men, univariate linear regression analyses were conducted and 9 viaribles [hypertension, TC, LDL-C, apoAI, apoB, Lp(a), TC/HDL-C, LDL-C/HDL-C and apoB/apoAI] were found to be associated with the Gensini scores (P < 0.1 for all)." (PMID 27716220, 2016). "There were significant differences between CAD and control groups in important risk factors including age, BMI, smoking, hypertension, DM, atrial fibrillation (AF), stroke, TG, HDL, Lp(a), BUN, uric acid, ApoA1, and ApoB." (PMID 24533640, 2014). "Association of apoB 3' VNTR alleles and direct clinical diagnosis of essential hypertension was studied extensively." (PMID 19772655, 2009). "Risk factors identified include advanced age, increased BMI, hypertension,raised TC and high ApoB." (PMID 41209502, 2025). "Furthermore, our results showed a positive correlation between APOB and hypertension, implying a potential mediating role of hypertension between APOB and endometrial cancer." (PMID 39193372, 2024). "Several studies have linked apolipoproteins (APOA1, APOB and APOL1) with CKD and hypertension." (PMID 38402394, 2024). "To better understand the association, we performed an additional analysis, which showed that among participants with apolipoprotein B < median (92mg/dL), those with discordant RC ≥ median (20mg/dL) had significantly higher odds of having hypertension (OR 1.73; 95% CI 1.38-2.17)." (PMID 37842298, 2023). "Subgroup analysis showed that ApoB/ApoA-I was independently associated with stroke recurrence regardless of the age of patients, the presence of hypertension, and the level of LDL-C." (PMID 38274879, 2023). "A supplementary analysis (NHANES 2007-2016, N=6,854) showed that among participants with apoB < median (92mg/dL), those with discordant RC ≥ median (20mg/dL) had significantly higher odds of hypertension after adjusting potential confounders (OR, 1.73; 95% CI, 1.38–2.17)." (PMID 37842298, 2023). "In that study, apolipoprotein B and total triglycerides were also predictive of future hypertension whereas average LDL particle size was negatively associated with the development of hypertension." (PMID 34784307, 2022). "LDL/ApoB was negatively correlated with the concomitant of hypertension (p=.021)." (PMID 34996506, 2022). "However, in controls, hypertension, current smoking and elevated ApoB:ApoA1 ratio were significant in multivariable models, whilst increased BMI did not remain significant." (PMID 36362763, 2022). "However, plasma levels of anti-ApoB IgG, which are considered pro-inflammatory, were significantly increased in patients with obesity (p = 0.044) and arterial hypertension (p < 0.0001)." (PMID 35479271, 2022). "The baseline apoB concentration was positively correlated with the incidence of hypertension." (PMID 36551995, 2022). "High non-HDL-C and ApoB were independently associated with male gender, fasting plasma glucose, poor glycemic control and hypertension." (PMID 28376848, 2017). "The INTERHEART study of potentially modifiable risk factors associated with myocardial infarction reported population attributable risks of 35.7%, 49.2%, and 17.9% for smoking, apolipoprotein B to apolipoprotein A1 ratio, and history of hypertension, respectively." (PMID 25003122, 2014). "We anticipated that some of the genetic risk SNP for CAD would act through established CAD risk factors, including BMI, waist/hip ratio, LDL-C, HDL-C, total cholesterol, triglycerides, ApoA1, ApoB, ApoB/A1 ratio, blood pressure, heart rate, hypertension and type 2 diabetes." (PMID 24475106, 2014). "Additional analyses showed that RC-associated high prevalence of hypertension may not be related to apoB." (PMID 37842298, 2023). "The current research indicated, for the first time, that the ApoB/ApoA1 ratio and concentrations of serum GDF-15 were predictive indicators of CAD in Chinese patients with T2DM, independent of potential risk factors such as hyperglycemia, diabetic duration, hypertension and age." (PMID 35842724, 2022).